GFAP (glial fibrillary acidic protein)
Diseases named in the same sentence as GFAP in open-access papers (continued):
Sharing a sentence is not in itself a finding about the gene and the disease.
Stroke (continued). "The relative change in GFAP expression in aged mice as assessed 2-weeks post-stroke following vehicle and 1 mg/kg PEG-IGF-I treated animals was greater than that observed in young." (PMID 28325900, 2017). "S100B, NSE, and GFAP are detectable in the blood early after traumatic brain injury or stroke; however, their half-lives are estimated between 30 minutes and 48 hours." (PMID 28605426, 2017). "The number of GFAP-positive cells then started to decrease at 15 and 21 h after stroke (Student’s t tests: p < 0.001 for 12 vs. 15 h, p < 0.001 for 12 vs. 21 h)." (PMID 29212271, 2017). "In this study, we also investigated the correlation of UCH-L1 and GFAP levels with patient characteristics including age, gender, diabetes, hyperlipidemia and having a previous history of stroke." (PMID 27074724, 2016). "At the early acute phase (2 days post stroke), NaB treatment decreased brain lipid peroxides, and reduced serum levels of GFAP, a surrogate marker of blood-brain barrier (BBB) permeability." (PMID 27905989, 2016). "By contrast, at 6 weeks post stroke, few IBa-1- or GFAP-positive cells were detected at the periphery of the lesion, while the lesion site was largely populated with NeuN-positive cells." (PMID 27483381, 2016). "Efforts are being made to measure the higher levels of glial fibrillary acidic protein (GFAP) in blood, for example, as an early marker of traumatic brain injuries and stroke, as well as a way to follow up on a specific treatment for these patients." (PMID 27195011, 2016). "Increases in extracellular K+ levels, known to increase GFAP expression, also increase Ca2+ influx and intracellular cAMP levels during stroke." (PMID 27242440, 2016). "Following ischemia, knock-out mice lacking the astrocytic intermediate fibres upregulated after stroke (GFAP and Vimentin) showed reduced glial scarring but an increase in infarct size and reduced functional recovery." (PMID 26927079, 2016). "CSF GFAP increments have been clinically identified in some conditions of acute brain injury, such as stroke, as well as chronic conditions, such as Alzheimer's disease or vascular dementia." (PMID 26090233, 2015). "Glial fibrillary acidic protein was recently identified as a biomarker that is indicative of ICH in the acute phase of stroke." (PMID 26081945, 2015). "GFAP staining revealed that although the ischemic injury is restricted to the cortex, reactive GFAP+ astrocytes were present throughout both cortical and striatal regions in the stroke side." (PMID 25927436, 2015). "Consistent with a baseline increase in astrocyte reactivity in uninjured mutant mice, the number of GFAP+ astrocytes in the contralateral hemisphere was higher in mutants than controls after stroke (89 ± 10 vs. 18 ± 2, p < 0.001)." (PMID 26317208, 2015). "In summary, the present study demonstrated that stroke considerably increased the number of GFAP-positive neural stem cells in the V/SVZ." (PMID 25437857, 2014). "The number of proliferating radial glial cells (Ki67+/GFAP+) increased 7 days post-stroke compared to sham-operated animals (P<0.05, Scatter plots, Mann Whitney test)." (PMID 24809543, 2014). "Stroke substantially increased these GFAP+ long processes, suggesting that neural stem cells sense changes in signals from a network of angiogenic vessels after stroke." (PMID 25437857, 2014). "A prospective study involving 135 patients admitted 6 hours after onset of stroke symptoms reported detection of serum GFAP in 81% of patients with haemorrhagic stroke but in only 5% of those with ischaemic stroke." (PMID 25029344, 2014). "Protein markers of cerebral damage, including myelin basic protein (MBP), neuron-specific enolase (NSE), S100β, and glial fibrillary acidic protein (GFAP), are found in CSF and serum after stroke." (PMID 25309322, 2014).
Stroke (continued). "Supporting this, in stroke studies, considerable amount of data demonstrated significantly increases in GFAP in expanding intra-cerebral hemorrhage (ICH) than that in ischemic stroke." (PMID 24260364, 2013). "That the GFAP-positive glial cells appeared more co-localized with Hsp27 suggests that glial cell alterations seen in stroke are primarily reversed by DPC-induced neuroprotection." (PMID 24086730, 2013). "We conclude, therefore, that any increase in astrocyte mitosis due to age and/or injury would make only a minimal contribution to the numbers of GFAP +/PH3 + cells in the post-stroke SEZ, and that the great majority of these cells are mitotic NSC." (PMID 23830949, 2013). "Some Sin3A-enriched lncRNAs transcribed from intragenic loci that are particularly relevant to stroke, such as the transcription factor Fos, Dclk1 and the astrocytic activation marker GFAP." (PMID 24063527, 2013). "Stroke induces a massive increase in GFAP expression after a day, in several stroke models ranging from 30 minutes MCAO to the photothrombosis model." (PMID 22920191, 2012). "Data describing the differences in activation of astrocytes in normotensive and hypertensive rats after stroke are scarce, but it has been shown that there is less GFAP expression in the putamen and cortex of young SHRs until six months of age." (PMID 22647642, 2012). "Following the behavioral testing at day 14 post-stroke, all animals were euthanized in order to evaluate the cerebral infarction using the glial fibrillary acidic protein (GFAP) immunostaining." (PMID 22837703, 2012). "The group of animals treated with resveratrol between their initial and recurrent stroke demonstrated significant reductions in areas of altered astrocytic GFAP staining compared with the vehicle treated group (P<0.001)." (PMID 23082218, 2012). "This routine GFAP assay reveals the extent of glial scar, which closely approximates the cerebral damage in stroke." (PMID 22837703, 2012). "In contrast, only a few cells in NT-020-treated stroke brains double-labeled with BrdU and GFAP, while many cells in vehicle-treated stroke brains double-labeled with BrdU and GFAP." (PMID 22837703, 2012). "We did find that GFAP was expressed highly in CSF in a PD donor that died after a stroke, which is in accordance with an earlier report." (PMID 22577599, 2012). "After 14 days of NSCs implantation within the stroke-damaged striatum, a lower expression of GFAP IHC was observed (and inset) suggesting a reduction of glial scar." (PMID 22876219, 2012). "Following a mild ischemic stroke, sections immunostained with GFAP demonstrated areas of increased astrogliosis in peri-infarct/penumbral regions- an effect which was enhanced with recurrent stroke." (PMID 23082218, 2012). "There are some biological markers that have been studied as predictors of the type of stroke, including GFAP, NMDA, S100B, and Apo C–III." (PMID 21776296, 2011). "CNS injury including stroke, infection, and tumor growth lead to astrogliosis, a process that involves upregulation of glial fibrillary acidic protein (GFAP) in astrocytes." (PMID 21247490, 2011). "A different study in stroke in the rat determined that 10% of GFAP astrocytes within 250 μm of the core co-labeled with BrdU in the cortex, quite consistent with our observations." (PMID 22132159, 2011). "In stroke there is a prior report of extensive GFAP+ astrocyte proliferation close to the infarct area in the rat but no unbiased quantitation was provided." (PMID 22132159, 2011). "Next and in order to characterize the healing process after stroke immunostaining against collagen (Sirius-Red), astrocytes (GFAP), vascular endothelial cells (CD31) and microglia (Iba1) was performed." (PMID 22008614, 2011). "They too will proliferate and differentiate (astrogliosis) after stroke, which coincides with increased production of glial fibrillary acidic protein (GFAP)." (PMID 21040547, 2010).
Stroke (continued). "Increases in GFAP concentrations have been observed in CSF samples following human stroke and in blood samples of severe TBI patients although expression has not be correlated to delayed injury processes such as thalamic degeneration." (PMID 17605820, 2007). "Furthermore, in the MCAO + rtPA group, GFAP expression was reduced on day 28 post-stroke, indicating attenuated reactive astrogliosis." (PMID 41356802, 2026). "Integration of GFAP into clinical workflows may enhance early stroke detection and outcome prediction, supporting its role as a promising biomarker in AIS." (PMID 41827388, 2026). "Notably, the NeuN expression decreased significantly after stroke, while those of GFAP and Iba1 were elevated, indicating the death of neurons as well as the accumulation of astrocytes and microglia in the ischemic lesions." (PMID 41356802, 2026). "LVOne version 1 combined d-dimer positivity, GFAP negativity, and Field Assessment Stroke Triage for Emergency Destination scoring for LVO detection only; version 2 uses improved GFAP measurement and a clinical decision rule enabling simultaneous diagnosis of LVO and ICH." (PMID 42088320, 2026). "Immunofluorescence staining further confirmed that the PTBP1 is significantly increased in astrocytes following ischemic stroke, evidenced by the enhanced colocalization of PTBP1 with the astrocyte marker GFAP in the peri-infarct region in PT and tMCAO stroke model." (PMID 41328340, 2026). "GFAP, a well-studied intermediate filament protein predominantly expressed in astrocytes, showed robust upregulation in both acute (FC = 1.34) and chronic (FC = 9.80) post-stroke phases." (PMID 41342963, 2025). "It was also demonstrated that elevated GFAP levels correlated with ICH risk and may distinguish stroke subtypes effectively." (PMID 40949500, 2025). "Our results suggest that the presence of the past stroke lesions can affect the amount of GFAP, which may originate from gliosis or ischemic neuronal damage." (PMID 40076944, 2025). "However, among patients with past stroke lesions, only GFAP exhibited a significant correlation with the ADAS score (right column: r = 11.400, p = 0.0011)." (PMID 40076944, 2025). "In a study involving 35 patients diagnosed with acute ischemic stroke, which included 10 individuals with large vessel occlusion, serum GFAP levels were evaluated alongside cases of intracerebral hemorrhage (n = 12), transient ischemic attack (n = 4), and stroke-like symptoms (n = 11)." (PMID 40649119, 2025). "GFAP is an important marker for brain damage in stroke diagnosis." (PMID 41150802, 2025). "However, the number of GFAP+ astrocytes in the ipsilateral and contralateral sides of young and old stroke mice was similar." (PMID 40661422, 2025). "However, GFAP and copeptin were excellent markers in differentiating between stroke patients and stroke-free patients." (PMID 40508137, 2025). "In this study, we observed that GFAP-positive astrocytes in old mice exhibited thinner processes than those in young mice, with their processes extending toward the infarct core region at seven days after photothrombotic stroke." (PMID 40867143, 2025). "A point-of-care GFAP testing platform in ambulances could aid in the rapid triage of stroke patients." (PMID 40142325, 2025). "Our study provided evidence supporting that serum GFAP may have an important role in the prediction and treatment of cognitive impairment after stroke." (PMID 40421099, 2025). "Compared to the controls, stroke patients had significantly higher levels of GFAP." (PMID 41306424, 2025). "GFAP (p = 0.010, Cliff’s d = 0.409) was significantly increased in stroke patients." (PMID 41306424, 2025). "In this study, we found that old mice developed long-lasting memory dysfunction, which was also associated with more CD68+ activated microglia/macrophages and GFAP+ reactive astrocytes in the peri-atrophic regions and hippocampi than young stroke-only mice at 8 weeks after stroke injury (& 9)." (PMID 40661422, 2025).
Stroke (continued). "Given that elevated levels of YKL-40, sTREM2 and GFAP are also observed in other neurological disorders, including stroke, multiple sclerosis, and traumatic brain injury, their measurement should be integrated into a broader panel of biomarkers, in order to avoid misinterpretation." (PMID 40943483, 2025). "Additionally, prior validation of the LVOne GFAP LFA has been conducted in a stroke population against a commercial PoC platform (Abbott iSTAT TBI Plasma), demonstrating a similar degree of correlation to that observed in our study." (PMID 40650780, 2025). "In this study, which investigated stroke risk specifically in individuals with prediabetes and no other underlying disorders or diseases, similar elevated GFAP levels were observed." (PMID 41296388, 2025). "This study demonstrated that higher levels of GFAP were associated with PSCI, suggesting that GFAP could be a promising and straightforward screening indicator of cognitive impairment after stroke." (PMID 40421099, 2025). "Furthermore, recent Simoa®-based studies demonstrated that GFAP can accurately distinguish stroke subtypes in the prehospital phase, achieving 96.6% sensitivity and 98.4% negative predictive value within 3 h." (PMID 41152969, 2025). "A blood test for GFAP detection may enable the early identification of stroke type, allowing timely and appropriate treatment before hospital arrival." (PMID 40142325, 2025). "Consistent with immunohistological analyses, western blot analyses showed that the GFAP protein level in the atrophic regions of old mice was higher than that in the atrophic regions of young stroke mice (p<0.001), and their contralateral uninjured cortex (p=0.001)." (PMID 40661422, 2025). "Additionally, the variability in GFAP levels across individuals and stroke severities highlights the need for standardized cut-off values to improve its diagnostic reliability." (PMID 40026944, 2025). "With a few exceptions, patients in our study displayed an increase in GFAP between the first and second samples, indicating that GFAP might be a robust early stroke biomarker." (PMID 40900222, 2025). "Furthermore, overexpression of C3a under the glial fibrillary acidic protein (GFAP) promoter leads to increased production of GAP43, an axonal marker associated with post-stroke neurite extension." (PMID 41002405, 2025). "Similarly, GFAP is released progressively within 12 h post-stroke, making it a valuable biomarker for predicting intracranial pathology in both the hyperacute and acute phases." (PMID 40066310, 2025). "GFAP stands out as a highly promising early biomarker, but several other proteins and pathways also emerged, offering novel insights into the relative molecular differences between stroke subtypes." (PMID 41152969, 2025). "Serum GFAP levels showed a strong positive correlation with NIHSS scores at 1-month post-stroke." (PMID 41227149, 2025). "Similarly, and in contrast to NFL, others have also reported a significant correlation between GFAP and infarct volume at the early time points after stroke onset in patients with large vessel occlusion and patients undergoing EVT." (PMID 40900222, 2025). "We designed a strategy to deliver Neurod1 to GFAP+ cells in the stroke-injured cortex." (PMID 38540276, 2024). "The role of neurofilament light chain (NfL) and glial fibrillary acidic (GFAP) as potential biomarkers especially in severe stroke patients is unknown." (PMID 38400734, 2024). "Identifying the stroke subtype in a rapid manner with the contribution of GFAP could therefore expedite appropriate treatment, potentially reducing mortality and improving functional outcomes." (PMID 39459548, 2024). "Here, we explored whether GFAP packed in EVs could have any potential significance over the first month post-stroke." (PMID 38891912, 2024). "Both GFAP and S-100B show time-dependent increases post-stroke." (PMID 39459548, 2024).
Stroke (continued). "To determine whether SWELL1 channel‐mediated glutamate release contributes to the increased glutamate levels after stroke, we then performed tMCAO surgery on GFAP‐cKO mice and prepared acute brain slices for SIC and tonic NMDAR current recordings." (PMID 39056405, 2024). "Meanwhile, a substantial body of evidence is available demonstrating that GFAP reliably identifies intracerebral hemorrhage among patients with symptoms of acute stroke (i.e. differentiating intracerebral hemorrhage from ischemic stroke and stroke mimics)." (PMID 38581002, 2024). "Notably, there was a significant decrease in the relative fraction of XFP+GFAP-NeuN- cells at PSD63 in Neurod1-injected mice when compared to Cre controls (stroke/Cre_63d, 19.0 ± 2.7 vs. stroke/Neurod1_63d, 11.1 ± 1.5; p = 0.022)." (PMID 38540276, 2024). "Furthermore, among patients with known time of stroke onset, serum GFAP levels appear to increase with longer delays since symptom onset, particularly in LVO stroke." (PMID 39777311, 2024). "Furthermore, GFAP concentrations in CSF (mean 8.7 h after stroke onset) and serum (from 72 h on, with the highest correlation at 96 h after stroke onset) correlate with IS long-term outcomes according to the mRS score at three months after the stroke onset." (PMID 38891912, 2024). "Increased Iba-1+ microglia and GFAP+ astrocytes were seen in CD13KO mice after stroke." (PMID 37817190, 2023). "In unselected patients with suspected stroke, GFAP alone identified ICrH." (PMID 36604741, 2023). "In this study, we found that more severe symptoms of PTSD were inversely associated with lower GFAP volumes in adults without suspected stroke pathology, which contributes to our understanding of neuroimmunological mechanisms in chronic PTSD." (PMID 37251545, 2023). "GFAP is a constituent part of the astrocyte cytoskeleton, and it is released into the peripheral circulation after brain injury, such as traumatic brain injury, stroke, and cardiac arrest." (PMID 37887089, 2023). "The measurements of blood GFAP and NT-proBNP assessment represent a relatively simple method and can significantly improve the discriminatory accuracy diagnosis of stroke subtypes in particular, in an emergency environment where imaging equipment is not provided." (PMID 37685295, 2023). "This may explain the slightly higher rate of GAL3+ astrocyte proliferation (5.4% of all GFAP+ cells) in the neocortex exhibiting cerebrovascular edema, which was still half of the proportion observed in stroke (10.4%)." (PMID 38066208, 2023). "Because stroke and other cerebrovascular diseases cause distributional shifts in GFAP levels, multivariable-adjusted finite mixture models analyzed GFAP distributions in responders with and without possible cerebrovascular disease." (PMID 37251545, 2023). "The boundary between the host and the stroke cavity (containing the grafted cells) could be easily identified with anti-GFAP staining." (PMID 37951968, 2023). "Typically, mostly GFAP immunoreactivity is examined in human pathology as it is increased in reactive astrocytes in response to different brain insults, including stroke, TBI, inflammation, tumors, epilepsy, Alzheimer’s disease, Parkinson’s disease and Huntington’s disease." (PMID 38066208, 2023). "Also, the number of GAL3+GFAP+ astrocytes was significantly increased in samples from patients with TBI or stroke compared with COVID-19 or AC." (PMID 38066208, 2023). "Therefore, GFAP is considered a biomarker for differentiating between patients within the acute phase of stroke symptom onset." (PMID 38032374, 2023). "In addition, a small population of activated astrocytes were shown to express IRAP following stroke as demonstrated by GFAP and IRAP colocalization." (PMID 37957163, 2023). "Using GFAP and PreSS together in a decision tree may improve prehospital differentiation of stroke, and thereby improved transport—and treatment strategies." (PMID 36604741, 2023).